RERG (RAS like estrogen regulated growth inhibitor)
Diseases named in the same sentence as RERG in open-access papers (continued):
Sharing a sentence is not in itself a finding about the gene and the disease.
tumor (17 papers, 2014 to 2024). "BTG4 and RERG genes implicated in tumor growth repression were found to be the most strongly up-regulated genes by anti-apoA-1 IgGs." (PMID 33245719, 2020). "ADIRF, tumor-associated genes CLU, FAM13C, as well as NGF, PRELP, RERG, PTGIS, GPC3 genes were among the top 20 overexpressed genes in EcE stromal cell population." (PMID 39169201, 2024). "In some epithelial tumors, RERG inhibits tumor cell proliferation, growth, migration, invasion, and angiogenesis by inhibiting the ERK/NF-κB signaling pathway." (PMID 37457559, 2023). "RERG encodes a member of the RAS superfamily participating in the regulation of cell proliferation and tumor formation." (PMID 31480430, 2019). "In this study, we found that RERG exerted its tumor suppressor role by attenuating the activation of Ras/ERK signaling effectors." (PMID 27705918, 2017). "Our findings suggested that RERG exerted its tumor suppressor role by deactivating Ras/ERK signaling effectors." (PMID 27705918, 2017). "RERG is a Ras-related GTPase, and its active form has been suggested to have a tumor suppressor role." (PMID 27705918, 2017). "In the present study, we investigated the epigenetic regulation and potential tumor suppressor function of RERG in NPC." (PMID 28659184, 2017). "In this study, we observed that RERG reduced cellular migration and invasion in NPC in vitro and suppressed tumor growth and angiogenesis in vivo, but the potential ability and the detailed mechanisms of RERG-inducing distant metastasis in vivo requires further study." (PMID 28659184, 2017). "RERG is a Ras-related small GTPase and a candidate tumor suppressor." (PMID 27705918, 2017). "Hence, we examined the regulatory roles of miR-382-5p and RERG in breast carcinogenesis and progression." (PMID 27705918, 2017). "In addition, we observed that in a mouse xenograft model, RERG inhibited microvessel development as well as tumor growth." (PMID 28659184, 2017). "Overexpression of RERG, a member of the RAS superfamily of GTPases, inhibits cell proliferation and tumor formation." (PMID 36774470, 2023). "Therefore, the heterogeneity expression of ERβ/RERG could trigger LGBLEL tumor development." (PMID 37457559, 2023). "RERG suppressed the ERK/NF-κB signaling pathway and inhibited tumor growth and angiogenesis with down-regulation of MMPs and IL8 in tumors of nude mouse xenografts." (PMID 28659184, 2017). "We also found that RERG exerts its tumor suppressor functions by inhibiting ERK/NF-κB signaling pathway, resulting in suppression of tumor cell proliferation, clonogenicity, migration, invasion and angiogenesis." (PMID 28659184, 2017). "Our results suggest that RERG is frequently silenced by promoter CpG methylation in NPC, and acts as a functional tumor suppressor by suppressing the ERK/NF-κB signaling pathway." (PMID 28659184, 2017). "However, the functions of RERG are largely unknown in other tumor types." (PMID 28659184, 2017). "We noticed however, that a few CT-RERG-negative tumor samples nevertheless displayed DNA hypermethylation of PTPRO and RERG, thereby suggesting that transcriptional overlap may not be the only mechanism directing epigenetic silencing onto these promoters." (PMID 34462486, 2021). "Interestingly, eight among the overlapped hypermethylated genes (WT1, PAX6, GNAS, EPB41L1, CSMD1, CPEB1, RERG, and SMAD6) were previously reported to exhibit tumor suppressive functions." (PMID 34462486, 2021). "Lack of GABRQ/GABRA3 and PTPRO/RERG promoter hypermethylation was indeed observed in a fraction of tumor samples that nevertheless produced the overlapping transcripts." (PMID 34462486, 2021).
tumor (continued). "A possible explanation is that overexpression of RERG might suppress the crosstalk between cancer cells and tumor stroma in vivo, but not in vitro." (PMID 28659184, 2017). "As overexpression of RERG reduced the expression of α-SMA in mouse xenograft model, it is suggested that RERG might involve in the suppressing the crosstalk between tumor cells and tumor microenvironment." (PMID 28659184, 2017). "Thus, our study suggests that detection of NFAT3/RERG complex in the primary tumor could be a new prognostic marker of the absence of ALN colonization." (PMID 35847954, 2022). "However, evidence that RASL12 functions as a small GTP-binding protein is lacking; In fact, studies have reported that RASL12 could be homologous to the RAS-like GTPases RERG, RASL11A, RASL11B, RASL10A and RASL10B, which play tumor-suppressive roles in human cancers." (PMID 34819106, 2021).
cancer (9 papers, 2016 to 2025). A tumor composed of atypical neoplastic, often pleomorphic cells that invade other tissues. "We also detected downregulation of RERG (RAS-like estrogen-regulated growth inhibitor) by DNA methylation in the cancer tissues." (PMID 30340457, 2018). "The miR-382-5p expression pattern revealed increasing trends among higher pathological grade and higher clinical stage cancers; however, we observed decreasing trends in the RERG expression pattern." (PMID 27705918, 2017). "This study provides insights into the possible mechanisms underlying the role of RERG in NPC carcinogenesis, and suggests that RERG might be employed as a target molecule in cancer therapy." (PMID 28659184, 2017). "Hypermethylation of ADAMTS9 and RERG were associated with risk of CRC only without a family history of cancer." (PMID 27453436, 2016). "RERG expression was assessed in human subjects (NPC primary tissues and non-cancer tissues) and cell lines (NPC cell lines and an immortalized epithelial cell line NP460)." (PMID 28659184, 2017). "Moderate expression of RERG was observed in the membrane and cytoplasm of normal nasopharyngeal epithelium cells, while very weak or no expression of RERG was observed in NPC cancer nests." (PMID 28659184, 2017).
RERG also shares sentences with these, for which no sentence is quoted: adenoma (1 paper); benign breast diseases (1); carcinoma in situ (1); colorectal adenocarcinoma (1); eczema (1); endometrial carcinoma (1); IgG4-related diseases (1); invasive breast carcinoma (1); Luminal Breast Cancers (1); lung carcinoma (1); Macrocephaly (1); malignant pleural mesothelioma (1); renal carcinoma (1); uterine carcinosarcoma (1).